TLR2 (toll like receptor 2)
Diseases named in the same sentence as TLR2 in open-access papers (continued):
Sharing a sentence is not in itself a finding about the gene and the disease.
bacterial infection (continued). "Autophagy is induced when S. aureus activates pattern recognition receptors (PRRs) such as toll-like receptor 2 (TLR2) and nucleotide-binding oligomerization domain-containing protein 2 (NOD2), and is considered as a defense mechanism against bacterial infection." (PMID 39310788, 2024). "The cross talk between these two pattern recognition receptors leads to a nonadditive response, which alters the TLR2-mediated cascade that controls the bacterial infection." (PMID 36692289, 2023). "Relative gene expression and protein level of pro-inflammatory cytokines (TNF-α, IL-6, IL-8), IL-10, TLR-2 and SERT were measured in fully differentiated Caco-2 monolayers following 24 h of bacterial infection in the presence of different levels of 5-HT (0, 100, 250, 500 ng/mL)." (PMID 34799637, 2021). "The expression of B2m, Ctsl, Calr, and Pdia3 suggests efficient antigen processing and presentation process, and the upregulation of Rac1, and Cd14 indicats the involvement of TLR2 and TLR4, which are essential for Th1/Th17 responses elicited by wPVs or bacterial infection." (PMID 34759909, 2021). "To our surprise, we found that CCN1 can by itself induce inflammatory responses in the absence of bacterial infection through physical interaction with TLR2 and TLR4 to activate MyD88-dependent signaling." (PMID 32144270, 2020). "Moreover, rSIP is an agonist of toll-like receptor 2 (TLR2) and TLR4, which suggests a dual role in the generation of innate and adaptive immune responses against bacterial infection." (PMID 32224855, 2020). "Thus, the inflammation-related membrane proteins, TLR2 and TLR4, were selected as they play important roles in the immunity of bacterial infection." (PMID 31531116, 2019). "TLR2, TLR4, and TLR5 play important roles in bacterial infection: TLR4 recognizes LPS, a major cell wall component of Gram-negative bacteria, whereas TLR2 and TLR5 recognize peptidoglycan (PGN), another bacterial wall component, and flagellin (FLG), respectively." (PMID 22367599, 2012). "Although not explored in this study, this presents a hypothesis that PPE19 may signal through TLR-2, similarly to the closely related PPE18 and PPE60, to mediate macrophage phagocytosis of Mtb, a well-characterized host response to bacterial infection (57, –, 60)." (PMID 40787981, 2025). "Therefore, ligands binding to TLR2 and -4, including antigens from bacterial infections of Gram-positive and Gram-negative bacteria, appear to be of inferior relevance in AF and SZ." (PMID 35337097, 2022). "It cannot be ruled out that if bacterial infection stimulates TLR2/4 on decidual cells during pregnancy and downstream signaling induces cytokine production, endogenous lipid ligands for TLR2/4 present on uterine stromal cells modify the character of these cells during decidualization." (PMID 27287066, 2016). "Our results showed that TLR2 and TLR4 expression by BMDMs controlled the potential response to microbial ligands and that this response was dramatically enhanced by GM-CSF priming, suggesting that GM-CSF can modulate the activation of macrophages in the host defense against bacterial infection." (PMID 22808181, 2012). "Interestingly, the expression of TLR2, 7 and 8 at the mRNA level was highly up-regulated following S. pneumoniae treatment (Data not shown), implying a possible important role for TLR2 up-regulation in bacterial infections." (PMID 18664270, 2008). "Because the expression of DDX5 decreased following treatment with TLR2/4 agonists in both MEFs and mouse macrophages, we hypothesized that post-translational modifications, such as phosphorylation, SUMOylation, or ubiquitination could be involved in downregulating DDX5 upon bacterial infection." (PMID 38182816, 2024). "In the absence of bacterial infection, DDX5 forms a complex with METTL3 and METTL14, which regulates target transcripts, including TLR2/4 mRNAs, through m6A modification." (PMID 38182816, 2024).
bacterial infection (continued). "In this study, we used heat-killed E. coli as potent TLR2/TLR4 ligands, mimicking a bacterial infection known to have an entourage of bacterial ligands and not just LPSs or LTA." (PMID 37887345, 2023). "We discovered that under normal conditions (i.e., without bacterial infection), DDX5 interacts with two known m6A writer proteins, METTL3 and METTL14, to form a ternary m6A writer complex, which recognizes and binds to TLR2/4 mRNAs to introduce m6A modifications." (PMID 38182816, 2024). "This could be explained by the different pathways activated by each stimulant: conA induces a strong and non-specific activation of T-cells whereas LPS mimics a bacterial infection by activating TLR-4 and TLR-2 innate receptors." (PMID 37965258, 2023). "The combined absence of both TLR2 and TLR4 resulted in significant resistance to ascending GBS infections, in contrast with mice lacking either TLR2 or TLR4 alone; this was unsurprising as these two receptors have been described to be compensatory during acute bacterial infections." (PMID 37747229, 2023). "Altogether, these results show that CCN1 can directly bind and activate TLR2 and TLR4 and may function as a DAMP to regulate inflammatory responses, independent of bacterial infections." (PMID 32144270, 2020). "Bacterial infection may also account for the previously reported constitutive high expression of TLR1, TLR2, TLR4, and TLR9 but not TLR3 in SGECs from SS patients." (PMID 32208441, 2020).
infectious disease (50 papers, 2007 to 2026). A disorder directly resulting from the presence and activity of a microbial, viral, or parasitic agent in humans. "Dysregulation of TLR2 signaling due to genetic polymorphisms can lead to altered immune responses, potentially increasing susceptibility to infectious diseases." (PMID 41295183, 2025). "Single nucleotide polymorphisms (SNPs) in human TLR2 have been reported to associate with the increased susceptibility to infectious diseases." (PMID 35205112, 2022). "Despite its reported association with TLR1, TLR2 variants are associated to a much wider panel of infectious diseases." (PMID 19924287, 2009). "In vivo, TLR2 deficiency in mice has been reported to result in persistently increased Borrelia loads in tissues, and genetic variation in TLRs corresponds with certain infectious disease risks." (PMID 39202370, 2024). "Previous studies demonstrate the importance of TLR2 agonists in inducing a pro-inflammatory response that culminates in the control of infectious diseases." (PMID 36743957, 2023). "These TLR2 agonists or antagonists can be used to study the function of TLR2 in infectious diseases, and they also provide new possibilities as potential therapeutics that target TLR2 signaling to treat hyper-inflammation." (PMID 35205112, 2022). "The modulation of TLR2 signaling has become a popular approach for the design of host-directed therapeutics against NTM infectious diseases." (PMID 35205112, 2022). "TLR10 is still an orphan receptor, as no ligands for it have been described, although it has been shown to have a role in some infectious diseases and to modulate responses mediated by TLR2." (PMID 32411792, 2020). "Because TLR2 ligands are known to influence the induction of a broad, effective immune response by activating several cell types, TLR2 modulation is currently being explored in the contexts of infectious diseases, vaccination and cancer therapy." (PMID 32696994, 2020). "Considering its dominant function in control of transcriptional processes that govern defense responses and metabolism, the TLR2 protein can be expected to be also of importance for other infectious diseases and interactions with the microbiome." (PMID 31747871, 2019). "SNPs in the TLR2, TLR4 and TLR9 polymorphisms have been studied for altering the susceptibility and resistance to various inflammatory and infectious diseases." (PMID 29922617, 2018). "The effect of TLR2 on cytokine production and resistance to infectious diseases has been a controversial point in the literature." (PMID 28344593, 2017). "For instance, mutations in TLR2, TLR4, TLR5 and IRAK4 have all been associated with increased risk to develop infectious diseases." (PMID 19859543, 2009). "TLR2/TLR1 as heterodimers has an important role in immune response in infectious diseases." (PMID 36313452, 2022). "TLR2 mediates host immune responses in major infectious diseases." (PMID 35893772, 2022). "A better understanding of the mechanisms behind TLR2 regulation of immunity in infectious diseases could be a significant benefit for accelerating the discovery of TLR2-related vaccines or targeted therapeutic treatments." (PMID 35205112, 2022). "However, the impairment of TLRs due to polymorphisms of TLR genes can alter the immune response to a wide variety of microbial ligands, including viruses, and polymorphisms in TLR2 and TLR4 have been linked to infectious diseases in humans." (PMID 32824985, 2020). "Besides, the protective role of AHCC® in infectious diseases seems to be related to its immunomodulatory properties by priming TLR-4 and TLR-2 and the associated TLR-4/MyD88 and NF-κB/MAPK signal transduction pathways." (PMID 31484389, 2019). "Therefore, TLR2/MyD88/NF-κB signaling pathway plays an important role in infectious diseases and inflammatory diseases, and inhibiting TLR2 could treat soft tissue infections by inhibiting inflammation and protecting tissues." (PMID 35222679, 2022).
infectious disease (continued). "However, some studies on the role of TLR2 in infectious diseases are still controversial." (PMID 35205112, 2022). "L-pampoTM, a proprietary vaccine adjuvant of TLR2 and TLR3 agonists, promotes strong humoral and cellular immune responses against infectious diseases." (PMID 37568794, 2023). "L-pampoTM is our innovative adjuvant system containing TLR2 and TLR3 agonists, and it provides robust humoral and cellular immune responses against infectious diseases." (PMID 37568794, 2023). "The potential application of Rn as an inhibitor of TLR-2 and TLR-4 activation provides a promising lead for drug development in infectious diseases induced by complicated microbial patterns." (PMID 26987407, 2016). "Alterations in the functions of TLR2 2258G (guanine)/ A, IFN-γ (+874T/A) and signalling molecules that result from polymorphisms are often associated with susceptibility or resistance, which may, in turn, establish the innate host response to various infectious diseases." (PMID 26114934, 2015). "TIRAP is a critical gene in the TLR2 and TLR4 signalling cascades and recent studies have investigated its role in a number of infectious diseases including TB." (PMID 19693265, 2009). "Since S. oralis EVs have potent TLR2-activating ability, VGS-derived EVs might be involved in systemic inflammation and progression of infectious diseases." (PMID 35987920, 2022). "Although we did not formally test this model, we previously demonstrated that TLR7 ligand administration does demonstrate “cross tolerance” for TLR2 and does not reduce host defense in a murine infectious disease model." (PMID 22619481, 2012). "As a lipopeptide derived from mycoplasma and a potential agonist of TLR2/6 heterodimers in DCs, MALP-2 is the most widely studied TLR2 adjuvant and has attracted great interest as a novel and efficient built-in adjuvant for vaccines against infectious diseases." (PMID 30656066, 2019).
inflammation (46 papers, 2006 to 2026). Aberrant reaction of the microcirculation characterized by movement of fluid and leukocytes from the blood into extravascular tissues. "Interestingly, airway levels of IL-8, NE, MMP-9, TLR2 mRNA and neutrophils were highly correlated, indicating that these mediators are both associated with neutrophilic airway inflammation and each other." (PMID 21483784, 2011). "Of note, prior studies revealed that in vivo DOX treatment increased TLR2 levels in cardiomyocytes and inhibition of TLR2 activity improved cardiac dysfunction and inhibited cardiac fibrosis and myocardial inflammation." (PMID 39018487, 2024). "We here report that myeloid Lkb1 has an important role in the induction of TLR2 mediated lung inflammation." (PMID 36096803, 2022). "Our current study indicated that DOX induced the increased formation of the TLR2/MyD88 complex, which leads to the activation of the NF-κB pathway and stimulates the expression of cardiac inflammation and fibrosis." (PMID 33928085, 2021). "Circulating E. faecalis are recognized by TLR2, a pattern recognition receptor that binds molecular patterns of Gram-positive bacteria, resulting in hepatic inflammation and chronic liver damage." (PMID 34887405, 2021). "There is a body of evidence supporting GM-CSF as an important mediator in lung inflammation by upregulating TLR2, TLR4, and CD14 expression, and by boosting IL-6 and IL-1β production from macrophages." (PMID 30013577, 2018). "Lung inflammation, measured by enumeration of bronchoalveolar neutrophils and scoring of histological sections, was significantly blunted in TLR2−/− mice." (PMID 29142002, 2017). "BML-111 and anti-IL-1β antibody restrains the OVA-induced airway inflammation via downregulation of the TLR2/MyD88/NF-κB pathway." (PMID 25760938, 2015). "In a model of organic dust-induced airway inflammation, TLR2 knockout mice had significantly lower airway neutrophils, IL-6, TNF-α, and CXCL-1 (mouse homolog of CXCL8) compared with wild-type controls suggesting that airway inflammation is dependent on TLR2." (PMID 23606791, 2013). "Here we utilized this model of PLN-induced lung inflammation to determine the contribution of TLR2 and TLR4 to PLN effects in vivo." (PMID 19956717, 2009). "In this context, a recent study using a mice model of acute lung inflammation shows that inflammatory recruited monocytes up-regulate gene expression of chemokines, TNFα and lysosomal proteases and down-regulate TLR-2 expression." (PMID 16606450, 2006). "TLR2-mediated signaling pathway is critical for M. pneumoniae-induced lung inflammation." (PMID 39499730, 2024). "IL-17 is a cytokine that has been shown by us to be a key player in promotion of K-ras mutant lung tumorigenesis by NTHi-induced COPD type lung inflammation, as well as by others where it was specifically found to be dependent on TLR2/4 in the context of NTHi-mediated inflammation." (PMID 37283745, 2023). "A previous study has shown that the TLR2/4 mediated NF-κB pathway could improve lung inflammation in COPD model rats." (PMID 35911168, 2022). "TLR2 expression increased thymic stromal lymphopoietin (TSLP) production through the NF‐κB and JNK signaling pathways to extend the survival of recruited basophils and resident DCs in the lung, predisposing a type‐2‐cell‐mediated airway inflammation." (PMID 30184256, 2018). "The present study indicated that the inhibitory effects of anti-IL-1β antibody on OVA-induced airway inflammation may be mediated by the inhibitory role of anti-IL-1β antibody on the TLR2/MyD88/NF-κB pathway." (PMID 25760938, 2015). "Using TLR2- and TLR4-deficient mice, we further demonstrated that PM2.5-induced increases in BAL cell counts, ROS, IL-6, and TNF-α were partially attenuated in TLR4 knockout mice, indicating a contributory but not exclusive role for TLR4 signaling in PM2.5-driven pulmonary inflammation." (PMID 41596147, 2026).
inflammation (continued). "Additionally, our transcriptomic data suggest that UA-induced renal inflammation may be initiated by extensive activation of TLRs (Tlr2/4/1/6/7/8/9)." (PMID 36891165, 2023). "Thus, in our study, the lower OVA-induced lung inflammation of TLR2−/− mice may be attributed to decreased IgG1 titers." (PMID 34315511, 2021). "We concluded that TLR2 regulates M. pneumoniae-mediated lung inflammation and TNF-α release through the TLR2-MyD88-NF-κB signaling pathway." (PMID 35372108, 2022). "Among the various TLRs, TLR2 and TLR4 are involved in the initiation and progression of vascular inflammation, including atherosclerotic diseases." (PMID 31023999, 2019). "Consistent with BML-111-induced downregulation of the TLR2/MyD88/NF-κB pathway, the OVA-induced airway inflammation was restrained, as shown by the reduced serum levels of IL-1β, IL-4 and IL-8, as well as BALF levels of IL-1β, IL-4, IL-8, OVA-IgE." (PMID 25760938, 2015). "The primary objective of the present investigation was to determine the contribution of TLR2 and TLR4 in lung inflammation and injury induced by PLN in vivo." (PMID 19956717, 2009). "The primary objective of the present study was to determine the role of TLR2 and TLR4 in lung inflammation induced by intrapulmonary delivery of PLN." (PMID 19956717, 2009). "TLR2 and TLR4 have been reported to mediate ISO‐induced cardiac inflammation." (PMID 39118286, 2024). "In RA, hyperactivated macrophages increased the expression of toll-like receptors (TLRs), such as TLR2, TLR3, TLR4, and TLR7, which induce synovial inflammation and cartilage destruction by releasing chemokines, pro-inflammatory cytokines, and degradative enzymes have been recognized." (PMID 36172378, 2022). "Although monocyte SIRT1 overexpression has been shown to prevent vascular inflammation by improving vascular functions, the precise role of SIRT1 in TLR2-induced vascular inflammation has not been determined." (PMID 31023999, 2019). "The reported role of TLR2 and TLR4 in intestinal I/R injury is controversial; however, majority of the studies conducted in pathological models other than those of intestinal inflammation have reported that the TLR2 and TLR4 signaling pathways induce inflammation." (PMID 30087540, 2018). "This suggests that cardiac inflammation in pressure overload is regulated by TLR2 via production of cyto/chemokines rather than recruitment of inflammatory cells to the heart." (PMID 28835616, 2017).